APLP2 (amyloid beta precursor like protein 2)
Diseases named in the same sentence as APLP2 in open-access papers (continued):
Sharing a sentence is not in itself a finding about the gene and the disease.
depression (2 papers, 2022 to 2024). "In recent work, multiple AD-related models were congruent with a human depression portrait, including APPsa knock-in, APP knockout, APP/PS1 mutation, and APLP2 knockout and this is consistent with the finding of overlaps between AD and depression portraits." (PMID 38236817, 2024). "The link between AD-related mouse lines and depression was high with multiple AD models (e.g., humanized APP/PS1, APP KO, APLP2 KO) being among the top 20 matches and this finding is consistent with studies identifying high comorbidity of AD and depression." (PMID 34997033, 2022).
epithelial ovarian cancer (2 papers, 2020 to 2024). "Amyloid precursor-like protein 2 (APLP2) was found directly associated with CLDN7 in ovarian cancer cell line OVCA420." (PMID 32257370, 2020). "Knockdown of APLP2 was associated with decreased cell survival in ovarian cancer cells." (PMID 32257370, 2020). "Among different interacting partners, APLP2 was particularly interesting as our previous report demonstrated that the changes in expression of APLP2 mRNA in CLDN7 siRNA transfected ovarian cancer cell line." (PMID 32257370, 2020). "Like CLDN7, increased levels of APLP2 proteins were found in both ovarian cancer cell lines and ovarian cancer tissue samples." (PMID 32257370, 2020). "In summary, this is the first study reporting interaction of CLDN7 with APLP2 and effect of APLP2 on cell survival in the ovarian cancer." (PMID 32257370, 2020). "OVCA420 cells transfected with siAPLP2 showed a significant decrease in survival compared with control siRNA-treated cells, indicating a significant role of APLP2 in ovarian cancer cell survival." (PMID 32257370, 2020). "We also identified functional role of APLP2 in ovarian cancer where lowering APLP2 protein levels led to decreased cell survival in ovarian cancer cell line, OVCA420." (PMID 32257370, 2020). "Increased expression of APLP2 in ovarian cancer and decreased survival of ovarian cancer cells after siRNA-mediated knockdown of APLP2 suggest potential role of APLP2 in ovarian cancer pathogenesis." (PMID 32257370, 2020). "In order to investigate functional role of APLP2 in ovarian cancer, we studied effect of APLP2 knockdown on cell survival ability of OVCA420 cells." (PMID 32257370, 2020). "Expression of APLP2 protein was increased in all ovarian cancer cell lines, except BG-1, when compared with the normal human epithelial cell line, HOSE-B." (PMID 32257370, 2020). "Interestingly, previous studies revealed that the high expression of ABCA1, APLP2, C3, EPHA2, and EFNA1 were associated with poor prognosis and epithelial ovarian cancer progression." (PMID 39135097, 2024). "The difference in expression levels of APLP2 among different cell lines might be due to the heterogeneous nature of ovarian cancer." (PMID 32257370, 2020). "In addition, APLP2 showed increased expression in ovarian cancer cell lines and tumor tissue samples compared with non-neoplastic ovarian tissues." (PMID 32257370, 2020).
Obesity (2 papers, 2020 to 2021). Accumulation of substantial excess body fat. "Some of these SNP loci were linked to genes, such as Wsb1, Snap29 and Aplp2, suggesting that they play a role in obesity development." (PMID 32273571, 2020).
renal cell carcinoma (2 papers, 2020 to 2023). "APLP2 expression was significantly related to disease-specific survival in renal cell carcinoma." (PMID 32850314, 2020).
Ataxia (1 paper, 2015). Ataxia refers to impaired coordination of voluntary muscle movement. "Aplp2 knockout mice were normal in size, fertile, and appeared healthy, whereas 80% of Aplp2/APP double knockout animals died within 24 h after birth and the remaining 20% exhibited difficulty in righting, ataxia, spinning behavior, and a head tilt." (PMID 26313004, 2015).
cataract (1 paper, 2024). Partial or complete opacity of the crystalline lens of one or both eyes that decreases visual acuity and eventually results in blindness. "In addition, upregulation of APOA1 and APLP2 in glaucoma samples was detected, as compared to ICL and cataracts." (PMID 39000104, 2024).
clear cell renal cell carcinoma (1 paper, 2025). "In contrast, APLP2 expression was reduced in clear cell renal cell carcinoma, and low APLP2 levels corresponded to worse patient outcomes, suggesting that APLP2 may have a dynamic role that varies among cancer types." (PMID 40265027, 2025).
congenital stationary night blindness (1 paper, 2016). "The APLP2-KO retina displayed numerous phenotypic similarities with the congenital stationary night blindness, a non-progressive retinal degeneration disease characterized by the loss of night vision." (PMID 27267879, 2016).
coronary artery atherosclerosis (1 paper, 2020). "Studies in APP and APLP1/2 knockout (KO) mice suggest functional differences among the three family members and, significantly, a particular importance for APLP2 in the physiology of the cholesterol metabolism and coronary artery atherosclerosis." (PMID 32716039, 2020).
endometrial carcinoma (1 paper, 2021). A malignant tumor arising from the epithelium that lines the cavity of the uterine body. "Of these somatic mutations of APLP2 and ARGHEF12 have been detected in head-and-neck SCC and cervical SCC respectively, and that of GRM7 and GALNACT have been detected in endometrial carcinoma." (PMID 34298793, 2021).
esophageal cancer (1 paper, 2023). A primary or metastatic malignant neoplasm involving the esophagus. "In the present study, the expression of APLP2 in esophageal cancer tissues was found to be significantly higher than in normal tissues, and this observation was confirmed by qPCR analysis." (PMID 38098487, 2023).
glioblastoma (1 paper, 2025). The most malignant astrocytic tumor (WHO grade IV). "Studies in glioblastoma showed a positive correlative relationship between high APLP2 expression and reduced overall survival." (PMID 40265027, 2025).
hyperlipidemia (1 paper, 2020). "Additional studies need to be undertaken to clarify the underlying molecular mechanism that associate the APLP2 gene polymorphisms with hyperlipidemia." (PMID 32716039, 2020). "In present study, we have found that rs2054247 of APLP2 gene was associated with hyperlipidemia among Chinese subjects, and thus assumed AA genotype of rs2054247 might be a risk genetic marker for coronary heart disease (CHD)." (PMID 32716039, 2020).
hypoglycaemia (1 paper, 2017). "Thus, alteration of synaptic function in other brain areas like the arousal system, or even non-neuronal and metabolic effects, such as hypoglycaemia previously shown for APP/APLP2-DKO mice, might be a potential cause of neonatal death." (PMID 28690498, 2017).
leukemia (1 paper, 2012). A malignant (clonal) hematologic disorder, involving hematopoietic stem cells and characterized by the presence of primitive or atypical myeloid or lymphoid cells in the bone marrow and the blood. "For the leukemia dataset, among the 10 top-ranked genes, two genes (ZYX and CCND3) are cancer ones, five (APLP2, CD33, SP3, CD63, PSME1) and one other genes (CST3) are directly or indirectly associated with cancer genes, respectively." (PMID 22830977, 2012).
metastatic tumors (1 paper, 2015). "Among these primary pancreatic, liver and lung metastatic tumors, the frequencies of positive APLP2 expression were 66.66% (16/24), 52.17% (12/23), and 100% (1/1), respectively." (PMID 25576918, 2015).
neuroblastoma (1 paper, 2011). Neuroblastoma (NB) is the most common solid, extracranial childhood tumor. "Human neuroblastoma SH-SY5Y cells shed three different soluble species (sAPLP2) of the endogenous APLP2." (PMID 21695060, 2011). "Here we demonstrate that the constitutive α-secretase cleavage of APLP2 in HEK293 and in neuroblastoma SH-SY5Y cells is mediated by ADAM10, but not by ADAM17." (PMID 21695060, 2011).
neuroendocrine lung tumors (1 paper, 2016). "APLP2 expression is decreased in lung neuroendocrine tumors, though the consequences are not well understood." (PMID 26840089, 2016). "In regard to other APP family members, according to the ONCOMINE database (Compendia Bioscience, Ann Arbor, MI), significant upregulation and downregulation of APLP1 and APLP2 (respectively) was observed in neuroendocrine lung tumors." (PMID 26840089, 2016).
ovarian tumor (1 paper, 2020). "Increased expression of APLP2 messenger RNA and protein was also found in ovarian tumor tissue samples." (PMID 32257370, 2020).
pancreatic ductal adenocarcinoma (1 paper, 2021). An infiltrating adenocarcinoma that arises from the epithelial cells of the pancreas. "The results from our RNA-seq analysis support the concept of increased APLP2 expression throughout disease progression in human pancreatic ductal adenocarcinoma." (PMID 33810510, 2021). "Genetically engineered mouse models of spontaneous pancreatic ductal adenocarcinoma were used to investigate APLP2′s role in cancer development." (PMID 33810510, 2021).
Parkinson disease (1 paper, 2006). A progressive degenerative disorder of the central nervous system characterized by loss of dopamine producing neurons in the substantia nigra and the presence of Lewy bodies in the substantia nigra and locus coeruleus. "However, two of these genes (APLP2 and SLC18A2) are associated with low level biological process categories clearly related to Parkinson' disease: "G-protein coupled receptor protein signaling pathway" and "monoamine transport", respectively." (PMID 16762065, 2006).
periodontitis (1 paper, 2020). An acute or chronic inflammatory process that affects the tissues that surround and support the teeth. "Periodontitis induced by P. gingivalis-LPS increased the expression of APP and its homologs (APLP1 and APLP2)." (PMID 32714134, 2020).
protein misfolding diseases (1 paper, 2016). "The proteins encoded by APLP2, PTN, DCN, GPNMB, P4HB, and PDIA3, have been associated with either protein misfolding diseases or TSEs but their specific role in prion protein degradation has not been described." (PMID 26807844, 2016).
retinal degeneration (1 paper, 2022). Degeneration of the retina. "Several of these have been reported to maintain retinal functions including APP which is expressed in neuronal cells of the inner retina and involved in inner retinal circuitry 46, and APLP2 whose deletion induced retinal synaptopathy and retinal degeneration." (PMID 36185601, 2022).
retinal diseases (1 paper, 2023). "Another small cluster of proteins (cluster 4) that suggest the role of neurodegeneration in these retinal diseases are APP and related proteins (e.g., CYTC, CLSTN1, SPP1, APLP2)." (PMID 36875133, 2023).
Retinal dystrophy (1 paper, 2021). Retinal dystrophy is an abnormality of the retina associated with a hereditary process. "The ITM2B-retinal dystrophy mutation could lead to a loss of interaction between APLP2 and the mutant ITM2B inducing a similar phenotype as the Aplp2−/− mice." (PMID 34446781, 2021). "APLP2 is particularly interesting since its deletion in the mouse retina induces a phenotype similar to the retinal dystrophy observed in subjects carrying the ITM2B c.782A>C, p.Glu261Ala mutation notably with similar electroretinogram alterations." (PMID 34446781, 2021).
thrombosis (1 paper, 2016). "Amyloid ß-protein precursor (AßPP) and amyloid precursor-like protein-2 (APLP2) are potent inhibitors of thrombosis, see related article “The influence of the amyloid ß-protein and its precursor in modulating cerebral thrombosis”." (PMID 26858980, 2016).
thyroid (1 paper, 2025). "This study focuses on analysing the expression of CD56, HBME-1, RRM2 and APLP2 IHC markers in NIFTP versus other thyroid follicular lesions and their diagnostic validity was also evaluated." (PMID 40420140, 2025). "Moreover, Amyloid precursor-like protein 2 (APLP2), Ribonucleotide reductase M2 polypeptide (RRM2) and Protein Regulator of cytokinesis 1 (PRC1) are new indicators studied to differentiate thyroid follicular lesions." (PMID 40420140, 2025).
cancer (25 papers, 2012 to 2025). A tumor composed of atypical neoplastic, often pleomorphic cells that invade other tissues. "Amyloid precursor-like protein 2 (APLP2) has been previously associated with pro-tumor phenotypes in cancer cells, and in this current study we investigated the expression and functions of this protein in macrophages." (PMID 40265027, 2025). "Studies from our laboratory on cancer cell lines demonstrated that APLP2 associates with the major histocompatibility complex (MHC) class I molecule, which presents tumor antigens and thereby activates T cell killing of malignant cells." (PMID 40265027, 2025). "Otherwise, the surface expression of HGprt enzyme was also observed in several somatic tissue cancers while APP and the APP-like protein-2 (APLP2) are deregulated in cancer cells and linked to increased tumor cell proliferation, migration, and invasion." (PMID 34877405, 2021). "APLP1 is closely related to APP and APLP2, both of which are associated with aggressive cancers in other organs." (PMID 30603059, 2018). "Both APP and APLP2 have been linked to characteristics of cancer cells such as abnormal growth, migration, and invasion." (PMID 26840089, 2016). "APLP2 is likewise overexpressed in cancer cells, and APLP2 and APP are linked to increased tumor cell proliferation, migration, and invasion." (PMID 26840089, 2016). "We also assessed the presence or absence of metastases in various anatomic sites within both groups of mice, and found that knockdown of APLP2 in the xenografted cancer cells caused major changes in the spread of the tumors." (PMID 25576918, 2015). "Moreover, APP and APP-like protein-2 (APLP2) are deregulated in cancer cells and linked to increased tumor cell proliferation, migration, and invasion." (PMID 36980958, 2023). "Recently, increasing evidence suggests an important function of APP as a potent tumor growth factor in the pathogenesis of several somatic tissue cancers, and APP as well as APLP2 are deregulated in cancer cells and linked to increased tumor cell proliferation, migration, and invasion." (PMID 34877405, 2021). "However, both APP and APLP2 are typically upregulated with advancement of cancer progression, and each has been implicated in several phenotypes related to cancer." (PMID 26840089, 2016). "APLP2 is aberrantly expressed in different types of cancers, with overexpression as well as proteolytic cleavage positively correlating with cell growth and migration." (PMID 41362608, 2025). "In cancer cells, APLP2 binds MHC class I at the cell surface and facilitates its internalization and routing to the lysosomes." (PMID 40265027, 2025). "Further studies are warranted to understand the interplay between CLDN7 and APLP2 and their involvement in cancer development and progression." (PMID 32257370, 2020). "Increased expression of APLP2 in several cancers and its role in migration, wound healing and cellular proliferation is indicative of its important functions in cancer." (PMID 32257370, 2020). "It is known that amyloid precursor protein (APP) and its family members amyloid precursor-like protein 2 (APLP2) expression is aberrantly altered in many types of cancers, e.g., pancreatic, colon, breast, prostate, lung, and others." (PMID 31509551, 2019). "Though previous studies have suggested a role of APLP2 in cancer progression, the exact role of APLP2 in cell migration remains elusive." (PMID 30155482, 2018). "In this review, we will now focus on the expression and functions of APP and APLP2 in specific types of cancer." (PMID 26840089, 2016). "Much remains to be discovered in cancer models about the impact of APP/APLP2 post-translational modifications, such as phosphorylation and glycosylation." (PMID 26840089, 2016). "APP and/or APLP2 have been described as having notable functions in many cancers, such as cancers of the prostate, breast, colon, thyroid, lung, nasopharynx, and gastrointestinal tract (for a more complete list)." (PMID 26840089, 2016).
cancer (continued). "APP and/or APLP2 expression is aberrantly altered in many types of cancers, such as pancreatic, colon, breast, prostate, lung, and other cancers." (PMID 26840089, 2016). "Given the unclear relation between APLP2 and K-Ras in cancer or other diseases, it may be interesting to follow up on their shared biology." (PMID 41362608, 2025). "Abnormal expression of APLP2 has been reported in several types of cancer." (PMID 40265027, 2025). "Given that APLP2 expression is altered in many cancer cells and APLP2 expression is correlated with poor outcomes, APLP2-targeted therapy might have potential to benefit cancer therapy through immune-mediated, as well as non-immune-mediated, mechanisms." (PMID 40265027, 2025). "Our approach covers a broad spectrum of cancer biology, of which LAMC2, ANXA2, ADAM9, and APLP2 are the most important features of the tested diagnostic model, and their implementation in clinical settings could be further examined." (PMID 30700038, 2019). "The roles of LAMC2, ANXA2, ADAM9, and APLP2 in cancer biology have been documented." (PMID 30700038, 2019). "Furthermore, APP and APLP2 have been shown to have a range of roles in cancer cells, including both pro-growth and pro-invasion functions." (PMID 26840089, 2016). "However, other reports indicate that IGF-1 actually promotes the generation of β amyloid, and therefore additional studies are needed to fully discern the effect of IGF-1 on APP and APLP2 processing and function in cancer." (PMID 26840089, 2016). "More work remains to be done, not only to examine the role of APP in lung cancer, but also to investigate the role that APLP1 and APLP2 might play in this particular type of cancer." (PMID 26840089, 2016). "As described in detail below, APP and APLP2 are overexpressed in many cancers." (PMID 26840089, 2016). "APLP2 (Amyloid beta precursor-like protein 2), known for its involvement in synaptic function and cellular adhesion, might affect cell-cell interaction and migration dynamics when downregulated, potentially facilitating cancer cell detachment and metastasis." (PMID 40090465, 2025). "Moreover, APLP2 helps cancer cell survival proliferation, migration and metastasis." (PMID 40420140, 2025). "Furthermore, a few studies have shown increased expression of APLP2 in cancers." (PMID 22797723, 2012). "Additionally, APP and APP-like protein-2 (APLP2) have been suggested to act as tumor growth factors in the pathogenesis of several somatic tissue cancers, and they may be used as potential biomarkers to guide clinical diagnoses and the treatment of cancers." (PMID 40717738, 2025). "The expression level of APLP2 is upregulated in the pancreatic tumor cell lines S2-013, the prostate cancer cell line DU145, and certain human cancers such as breast cancer but is downregulated in the lymphoma cell lines and in the lung neuroendocrine tumors." (PMID 30155482, 2018). "Since it is becoming increasingly clear that APP and APLP2 have pro-cancer functions, how APP and APLP2 expression and function are regulated is also evidently relevant to their roles in cancer." (PMID 26840089, 2016). "We are also examining the levels within cancer cells of the enzymes (such as beta-secretases) that cleave APP and APLP2, since expression levels of these enzymes regulate the biological influences of both APP and APLP2." (PMID 26840089, 2016). "All the down-regulated genes, in this Panel 3 showed their significant up-regulation in most of many types of cancers (TGM2, CSNK1A1, CTNNA1, NAMPT/Visfatin, TNFRSF1A, ETS1, SRC-1, FN1, APLP2, DMBT1/SAG, AIB1, AZIN1)." (PMID 23122428, 2012). "These proteins, including AHCYL1, APLP2, CTNN1D, EIF2B1, LGALS1, and SGPL1, play vital roles in maintaining cellular functions such as cell adhesion, protein synthesis, and lipid metabolism, which are often perturbed in cancer cells." (PMID 40090465, 2025).